FERRY3 (FERRY endosomal RAB5 effector complex subunit 3)
Description:
Component of the FERRY complex (Five-subunit Endosomal Rab5 and RNA/ribosome intermediary). The FERRY complex directly interacts with mRNAs and RAB5A, and functions as a RAB5A effector involved in the localization and the distribution of specific mRNAs most likely by mediating their endosomal transport. The complex recruits mRNAs and ribosomes to early endosomes through direct mRNA-interaction. Plays a role in mast cell degranulation.
Synonyms: Fy-3; C12orf4; MRT66
Tractability: PROTAC: ubiquitination databases record sites on it.
Gene: Protein-coding gene on chromosome 12 (4,487,735 to 4,538,519, reverse strand). Ensembl gene ENSG00000047621.
Subcellular location: Cytoplasm; Early endosome
Subcellular location (Human Protein Atlas): Nuclear bodies
Gene Ontology:
Molecular function: protein binding
Biological process: regulation of intracellular mRNA localization; regulation of mast cell degranulation
Cellular component: early endosome; protein-containing complex; cytoplasm
Genetic constraint (gnomAD): Loss-of-function variants: 28 observed, 48.17 expected, observed/expected ratio (o/e) 0.58, 90% interval 0.43 to 0.8. The upper end of that interval is the gene's LOEUF score, 0.8, which puts it in group 3 of 6, group 1 being the genes least tolerant of losing a copy. Missense variants: 415 observed, 507.47 expected, observed/expected ratio (o/e) 0.82, 90% interval 0.75 to 0.89. Synonymous variants: 151 observed, 179.32 expected, observed/expected ratio (o/e) 0.84, 90% interval 0.74 to 0.96.
Homologues: Orthologues: chimpanzee FERRY3 (99% identical), macaque FERRY3 (99% identical), dog FERRY3 (97% identical), pig FERRY3 (96% identical), rabbit FERRY3 (95% identical), guinea pig FERRY3 (95% identical), mouse D6Wsu163e (94% identical), rat Ferry3 (94% identical), tropical clawed frog ferry3 (78% identical), zebrafish FERRY3 (78% identical), Drosophila melanogaster CG9986 (35% identical), Caenorhabditis elegans C55A6.10 (29% identical).
Diseases named in the same sentence as FERRY3 in open-access papers:
FERRY3 is named in the same sentence as 12 diseases in open-access papers, as found by Europe PMC text mining. Sharing a sentence is not in itself a finding about the gene and the disease. The quoted sentences say what the papers report.
Intellectual disability (3 papers, 2019 to 2025). "Mutation of TBCK causes TBCK syndrome, mutation of PPP1R21 is associated with PPP1R21-related intellectual disability, and mutation of FERRY3 results in an autosomal recessive intellectual disability." (PMID 40062705, 2025). "Mutation of FERRY3 is associated with intellectual disability and behavioral problems, with some reports of infantile hypotonia." (PMID 40062705, 2025). "Our review identified 66 published descriptions of TBCK syndrome, 24 published descriptions for PPP1R21-related intellectual disability, and 16 published descriptions of FERRY3 autosomal recessive intellectual disability." (PMID 40062705, 2025). "Of the three disorders discussed here, the least is known about FERRY3 autosomal recessive intellectual disability." (PMID 40062705, 2025).
autism spectrum disorder (1 paper, 2025). A spectrum of developmental disorders that includes autism, and Asperger syndrome. "Other reported symptoms associated with FERRY3 mutations include autism spectrum disorders, gait abnormalities, mild dysmorphic features, and hypotonia." (PMID 40062705, 2025).
developmental delay (1 paper, 2025). "In 2015, a study seeking to identify the causative gene mutations in a large cohort of 143 families with neurological disorders identified both TBCK and FERRY3 as putative novel disease genes, with FERRY3 mutation associated with global developmental delay." (PMID 40062705, 2025).
neurologic disorders (1 paper, 2025). "Notably, mutations in three different members of the FERRY complex (TBCK, PPP1R21, and FERRY3) are associated with rare neurologic disorders in human patients." (PMID 40062705, 2025). "Here, we have described three rare neurologic disorders resulting from mutations in either TBCK, PPP1R21, or FERRY3." (PMID 40062705, 2025).
FERRY3 also shares sentences with these, for which no sentence is quoted: autosomal recessive intellectual disability (2 papers); brain malformations (2); adenocarcinomas of the ovary (1); arthrogryposis multiplex congenita (1); asthma (1); glioblastoma (1); lymphoma (1); recessive intellectual disability (1).